RUNX1 (RUNX family transcription factor 1)
Diseases named in the same sentence as RUNX1 in open-access papers (continued):
Sharing a sentence is not in itself a finding about the gene and the disease.
breast cancer (continued). "In ER+ breast cancer, however, RUNX1 predominantly functions as a tumour suppressor, and the present work attributes this function at least in part to antagonism of oestrogen-mediated AXIN1 suppression." (PMID 26916619, 2016). "Compromised RUNX1 function in ER+ breast cancer likely occurs in far more than the <5% of tumours with RUNX1 mutations." (PMID 26916619, 2016). "Our laboratory has previously shown that Runx1 depletion in breast cancer cells results in a decreased migration and invasion phenotype; similar results were found in ovarian cancer cells." (PMID 27720906, 2016). "In human breast cancer, Runx1 activity is still matter of debate and little is known about its direct role in breast cancer progression." (PMID 26735887, 2016). "In this study, by depleting RUNX1 in vitro and in vivo, we expose a link between oestrogen and β-catenin in ER+ breast cancer, that is, RUNX1-gated oestrogen-mediated AXIN1 transcriptional repression." (PMID 26916619, 2016). "Accordingly, RUNX1 knockdown with either shRx1RUNT or shRx13′-UTR resulted in increased MCF7 breast cancer cell proliferation." (PMID 26916619, 2016). "Down regulation of RUNX1 is part of a 17-gene signature that has been suggested to predict breast cancer metastasis." (PMID 26920143, 2016). "This study demonstrates combinatorial regulation of AXIN1 by RUNX1 and oestrogen signalling in ER+ breast cancer cells." (PMID 26916619, 2016). "Ferrari and colleagues performed the first comprehensive characterization of RUNX1 protein expression in breast cancer by immunohistochemistry using a large cohort of human samples." (PMID 26735887, 2016). "It further suggests that RUNX1 suppresses ER+ breast cancer progression by denying oestrogens their negative regulation of AXIN1." (PMID 26916619, 2016). "In the present study, we show that in SkBr3 breast cancer and HepG2 hepatocarcinoma cells E2 and G-1 induce the expression of miR144 and down-regulate the levels of Runx1 through GPER and the involvement of the PI3K/ERK1/2/Elk1 transduction pathway." (PMID 26030000, 2015). "Overall, our study identifies RUNX1 as a new prognostic indicator correlating with poor prognosis specifically in the triple negative subtype of human breast cancer." (PMID 24967588, 2014). "In particular, in breast cancer, recentwhole-genome and whole-exome sequencing studies have consistently identified pointmutations and deletions of RUNX1 in human luminal breast cancers." (PMID 25415051, 2014). "RUNX1 encodes a RUNX family transcription factor (TF) and wasrecently identified as a novel mutated gene in human luminal breast cancers." (PMID 25415051, 2014). "The relationship between RUNX1 expression and clinical outcome was then assessed by looking at cancer-specific survival in each breast cancer subtype." (PMID 24967588, 2014). "Here we have carried out the first comprehensive characterization of RUNX1 expression in tissues from a large cohort of human breast cancers and demonstrate its prognostic value in different tumour subtypes." (PMID 24967588, 2014). "Recently it was found that RUNX1 proteinexpression correlates with poor prognosis in ER− breast cancer andmore specifically in triple-negative breast cancer (TNBC)." (PMID 25415051, 2014). "Indeed, DDR1i caused differential expression in several direct RUNX1 target genes including DUT, an essential nucleotide metabolism enzyme seen upregulated across breast cancers, and MYC, along with ANP32B, PLEC, CEBPD, ID1, and STAT3." (PMID 40614729, 2025).
breast cancer (continued). "This notion is based on the hypothesis that DDR1 and CBFβ operate within the same pathway as RUNX1, contributing to cellular differentiation and structural stability in breast cancer." (PMID 40614729, 2025). "Indeed, previous studies have linked both RUNX1 and DDR1 to specific breast cancer phenotypes within specific subtypes." (PMID 40614729, 2025). "Specifically, RUNX1 interacts with SNORA71C to accelerate breast cancer progression and metastasis." (PMID 38430423, 2024). "Recent studies have indicated that RUNX1 plays a role in breast cancer cell migration and invasion." (PMID 39272372, 2024). "Conversely, RUNX1 may exert tumor suppressor activity in the mouse intestine and human luminal breast cancer." (PMID 36766749, 2023). "Additionally, these results highlighted that CBFB undergoes varying alterations depending on the breast cancer subtype in a similar way to that for RUNX1." (PMID 36831308, 2023). "CBFB/RUNX1 axis is reported to function as a tumor suppressor in breast cancer." (PMID 37454130, 2023). "RUNX1 and CBFB loss-of-function mutations are strongly associated with ER+ breast cancer." (PMID 36831308, 2023). "An independent study also reported two RUNX1 mutations and four mutations in CBFB in ER+ luminal tumors, while Nik-Zainal and colleagues showed that both RUNX1 and CBFB were in the top 50 of 93 genes at risk of acquiring driver mutations in breast cancers." (PMID 36831308, 2023). "On the one hand, RUNX1 could promote breast cancer metastasis in vivo, where the expression of RUNX1 rises during the metastasis of tumor cells from the primary site to the distal lung." (PMID 36429115, 2022). "On the other hand, it was demonstrated that the depletion of RUNX1 could promote the estrogen-induced Wnt signaling pathway in luminal breast cancer cells by suppressing AXIN1." (PMID 36429115, 2022). "Compared with normal samples, RUNX1 was upregulated in a variety of tumors, including bladder cancer, breast cancer, colorectal cancer, kidney cancer, liver cancer, lung cancer, oral cancer, ovary cancer, pancreatic cancer, testis cancer, and thyroid cancer (all P < 0.05)." (PMID 35534796, 2022). "Furthermore, PAK4 phosphorylates Runt-related transcription factor 1 (RUNX1), a regulator of the DNA damage response in breast cancer cells." (PMID 35883575, 2022). "The expression of key markers associated with proliferation (MKI67, PCNA, CCNB1, MYBL2, BUB1, CCND1), apoptosis (BCL2, CASP7, CASP8, CASP9, CASP3, BAX, APAF1), differentiation (CDH1, CD24, EPCAM, ESR1, NGFR, RUNX1), and breast cancer stemness (CD44, ITGA6, DNER, ALDH1A3, ABCG2, PROCR) was assessed." (PMID 35183258, 2022). "Furthermore, RUNX1 is known to inhibit the transcription of YAP in breast cancer, a molecular interplay that leads to immunosuppressive events during lung tumorigenesis." (PMID 36142846, 2022). "Moreover, it has been reported that RUNX1 phosphorylation involves in osteolytic bone destruction in ERα-positive breast cancer." (PMID 35534796, 2022). "On the other hand, an increasing amount of evidence points to a pro-oncogenic role played by the RUNX1 gene in breast cancer, intriguingly associated with the ER negative and triple negative (TN, i.e., ER-, PR-, HER2-) subtypes." (PMID 35867729, 2022). "Indeed, a role for CBFB in the suppression of breast cancer has recently emerged, and it has been reported that nuclear CBFB/RUNX1 complex represses the oncogenic NOTCH signaling pathway in breast cancer." (PMID 33808143, 2021). "Moreover, HDAC2 transcription is promoted by the YAP/RUNX1 complex to induce chemoresistance and stemness in breast cancer, indicating that HDAC2 plays a role in cell stem progress." (PMID 34993131, 2021). "RUNX1 has been shown to inhibit the growth of breast cancer stem cells and promote tumor expansion." (PMID 34485309, 2021). "It is also unknown whether the CBFB/RUNX1 axis cooperates with different pathways to suppress breast cancer." (PMID 33945523, 2021).
breast cancer (continued). "This was consistent with the increased RUNX1 expression in breast cancer." (PMID 34485309, 2021). "Future studies, focused on mitosis specific RUNX1 and/or ERα depletion followed by nascent transcriptomic analyses in estrogen receptor positive mammary epithelial and breast cancer cells, will be required to investigate mechanistic significance of this observation." (PMID 32655837, 2020). "Furthermore, NEAT1 and MALAT1, lncRNAs often deregulated in breast cancer, were also occupied by RUNX1 both in interphase and mitosis." (PMID 32655837, 2020). "Nevertheless, the relationship between PAK4 and RUNX1 in breast cancer is still unclear." (PMID 32549768, 2020). "By binding to the miRNA promoter, RUNX1 increases the transcriptional level of miR-27a in breast cancer and concomitantly the decreases expression of ZBTB10, a direct target gene of miR-27a, to promote endothelial differentiation and subsequent angiogenesis and tumor metastasis." (PMID 32102656, 2020). "Because breast cancer cells bone metastasis commonly generates osteolytic lesions, we tested whether phosphorylation of RUNX1 at T207 regulates cancer-induced osteoclastogenesis." (PMID 32549768, 2020). "Consistent with our finding that RUNX1 bookmarks and regulates rRNA genes, one of the pathways identified is mTOR signaling, a pathway that is required for cell growth and is a therapeutic target in breast cancers." (PMID 32655837, 2020). "In addition to the recognized role in hematopoiesis and hematological malignancies, RUNX1 has been recently identified as a key player in breast cancer development and tumor progression." (PMID 32655837, 2020). "It has been reported that RUNX1 suppresses breast cancer progression in ER-positive cells." (PMID 32549768, 2020). "Importantly, we verify changes in RUNX1 subcellular localization when nuclear PAK4 is positive in breast cancer bone metastasis tissues." (PMID 32549768, 2020). "Additionally, RUNX1 suppress the growth of several breast cancer cell lines through the repression of cancer stem cell activity and inhibition of zinc finger E-Box binding protein 1 (ZEB1) expression." (PMID 31592165, 2019). "Furthermore, nuclear CBFB/RUNX1 complex transcriptionally represses the oncogenic NOTCH signaling pathway in breast cancer." (PMID 31061501, 2019). "Finally, downregulation of CBFB and RUNX1 are found in several breast cancer cell lines and human breast cancer tissues." (PMID 31061501, 2019). "We chose RUNX1 and not RUNX2, since RUNX1 together with its binding partner CBFb has recently been discovered to be mutated ~ 4–6% in breast cancers; suggesting its tumor suppressor function in this context." (PMID 29581836, 2018). "There is a requirement for understanding Runx1-mediated regulatory mechanism(s) in breast cancer." (PMID 28407681, 2017). "As a suppressor gene in breast cancer cells, there was also research showing that interaction of Runx1 and FOXP3 genes can affected gene expression profile of mammary epithelial cell gene and finally Runx1 cause breast cancer progression on FOXP3 availability." (PMID 28029650, 2017). "We first observed that Runx1 is decreased in tumorigenic and metastatic breast cancer cells." (PMID 28407681, 2017). "Notably, the function of Runx1 in the mammary gland and how it is involved in initiation and progression of breast cancer is still unclear." (PMID 28407681, 2017). "Other studies showed that Runx1 is important for mammary gland maturation, and its interaction with ERα is necessary for luminal development and may prevent breast cancer progression." (PMID 28407681, 2017).
breast cancer (continued). "However, breast cancer cells metastatic to the lymph node showed significantly less Runx1 expression compared with the primary tumor site." (PMID 28407681, 2017). "Our studies offer Runx1 as a novel bio-therapeutic molecule for breast cancer intervention." (PMID 28407681, 2017). "Our data show MCF7 ER+ breast cancer cells can be induced into EMT by Runx1 depletion." (PMID 28407681, 2017). "We next evaluated Runx1 expression in breast cancer patient tissues." (PMID 28407681, 2017). "Additionally, RUNX1 can exert the tumor suppressor role in breast cancer through other pathways, such as FOXO." (PMID 29201108, 2017). "In particular, three independent studies of breast cancer patient cohorts have recently reported recurrent somatic mutations and/or deletions of RUNX1, as well as CBFB that encodes an obligate co-activator of RUNX1 (refs 18, 19, 20)." (PMID 26916619, 2016). "In pursuit of RUNX1 target genes in ER+ breast cancer, which may mediate the regulation of β-catenin levels, we determined both the RUNX1 transcriptome and its cistrome in MCF7 cells by mRNA profiling and ChIP-seq analysis, respectively." (PMID 26916619, 2016). "Since Runx1 is a potent regulator of gene transcription in different cell types, we hypothesized that the effect observed when tumor cells expressed the DN/Runx1 might have a wider effect on genome expression of breast cancer cells." (PMID 26735887, 2016). "This context encouraged us to investigate if Runx1 is able to modulate gene expression in mammary tumor cells, and whether this activity could be modulated by Foxp3 in normal epithelial cells." (PMID 26735887, 2016). "In addition, RUNX1 mutation leads to a poor outcome in CN-AML, and high expression of RUNX1 correlates with a poor prognosis in breast cancer." (PMID 26910834, 2016). "Little attention has been paid thus far to the potential roles of RUNX1 in breast cancer." (PMID 26916619, 2016). "Here we provide evidence that Runx1 could be relevant for breast cancer cell survival and migration, supporting the idea that Runx1 could act as a tumor enhancer." (PMID 26735887, 2016). "To address the combinatorial regulation of AXIN1 by RUNX1 and oestrogens in clinical settings, we first calculated an ‘inhibitory index' for RUNX1 in each tumour in the breast cancer cohort of TCGA20 based on the expression levels of genes that RUNX1 inhibited in MCF7 cells (see ‘Methods' section)." (PMID 26916619, 2016). "In addition, Runx1 expression was found less abundant in breast cancer cells compared to normal breast epithelial cells and its levels have been reported to decrease progressively with the tumor aggressiveness." (PMID 26030000, 2015). "Interestingly, this has also been shown for RUNX1, one of the only 2 putative driver genes that were misclassified in breast cancer." (PMID 25903787, 2015). "RUNX1, which was the second-highest scoring factor, is mutated in a subset of breast cancers but has not been previously implicated as a regulator of mammary stem cell biology." (PMID 25894653, 2015). "Recently a putative link to breast cancer has started to emerge, however the function of RUNX1 in breast cancer is still unknown." (PMID 24967588, 2014). "In luminal breast cancer, our study provides strong evidence to support that RUNX1 playsa key role in this breast cancer subtype as a tumor suppressor in ER+ductal luminal cells, which may be their cells of origin." (PMID 25415051, 2014). "RUNX1 expression was first tested on a panel of breast cancer cell lines." (PMID 24967588, 2014). "Assuper-enhancers often associate with key oncogenes in cancer cells, these recent findings suggestthat RUNX1 may also play an oncogenic role in ER− breast cancers." (PMID 25415051, 2014). "Interestingly, further studies with an inhibitor of CBFbeta-RUNX interaction resulted in EMT of breast cancer stem cells, suggesting that the loss of RUNX1 rather than increase of RUNX2 causes EMT in early stage breast cancer." (PMID 38630262, 2024).
breast cancer (continued). "Although RUNX1 mutations and rearrangements have been described in OAC39,48,49 and other carcinomas to our knowledge this consequence of mutation has not been noted before, except in a single example of an in-frame deletion of genomic exon 6 in the breast cancer cell line HCC193750." (PMID 35396535, 2022). "In addition, RUNX1 may inhibit ts‐112 to prevent hyperproliferation of breast cancer epithelial cells, thereby confirming its role in maintaining the breast epithelium." (PMID 33332661, 2021). "Interestingly, COL4A1 was also upregulated in breast cancer and ovarian cancer like RUNX1." (PMID 32746865, 2020). "Interestingly, RUNX1 functions as both an oncogene and a tumour suppressor in breast cancer." (PMID 31370857, 2019). "In addition, there are inconsistent or contradictory findings about whether RUNX1 promotes or inhibits EMT in breast cancer cells and epithelial ovarian carcinoma." (PMID 29759484, 2018). "All these pieces of evidence raise the hypothesis that Runx1 could function as a tumor suppressor in ER positive breast cancer; here we clearly demonstrate Runx1 has a direct role to prevent EMT in MCF7 ER+ breast cancer cells, and thus establishes Runx1 as a tumor suppressor." (PMID 28407681, 2017). "The epithelial phenotype could be restored in breast cancer cells by re-expressing Runx1." (PMID 28407681, 2017). "Finally, facilitate Runx1/Foxp3 interaction could be use to improve anti-tumor strategies in breast cancer therapy." (PMID 26735887, 2016). "Finally, RUNX1 loss-mediated deregulation of β-catenin and mitosis is ameliorated by AXIN1 stabilization in vitro, highlighting AXIN1 as a potential target for the management of ER+ breast cancer." (PMID 26916619, 2016). "In pursuit of molecular mechanisms contributing to its implied tumour suppressor activity in ER+ breast cancer, we performed pathway analysis of genes differentially expressed in the ER+ tumours with versus without RUNX1 mutations in TCGA, as well as in the ER+ breast cancer cohort of Ellis et.al." (PMID 26916619, 2016). "In addition, inhibition of Runx1 in an in vitro breast cancer model reduces cell migration." (PMID 27634876, 2016). "We could speculate that in TNBC highly positive for RUNX1, that RUNX1 would drive a transcriptional programme in breast cancer cells resulting in production and secretion of high levels of cytokines which would then lead to recruitment of lymphocytic cells at the tumour site." (PMID 24967588, 2014). "However little is known about the role of RUNX1 in human breast cancer." (PMID 24967588, 2014). "Their data showed that RUNX1, PTEN, MAP3K1, and CDH1 had the highest impact in distinguishing survival curves of premenopausal and postmenopausal breast cancer." (PMID 38919805, 2024). "These include EMT (TWIST1, SNAIL1, RUNX1, RUNX2, HIF1, and NOTCH1), breast cancer maintenance (OCT4, SP1, GATA1, ATF1, FOXO3a, ELK1, VDR, and NRF1), pro-metastatic responses (SMAD2/3, HNF1a, GLI1, NANOG, YY1, MYB1, and AP1), and immune modulation (STAT1/3)." (PMID 38398186, 2024). "Accumulating evidence strongly suggests that RUNX1 promotes tumor aggressiveness in TNBC, while functioning as a tumor suppressor in ER+ breast cancer." (PMID 36766786, 2023). "As an example, our results showed enrichment of RUNX1, ESR1, FOXA1, and FOXM1 target genes in breast cancer type-specific GRNs." (PMID 37627195, 2023). "In contrast to TNBC, RUNX1 and CBFβ have been described as tumor suppressor genes involved in reduced tumor growth and impaired EMT and CSC generation in ER+ breast cancer." (PMID 36766786, 2023). "Consistent with the bioinformatics analysis, the expression of RUNX2 was highest in the RUNX family in clinical breast cancer samples and cell lines; Moreover, RUNX2 was overexpressed, while RUNX1 and RUNX3 were decreased in breast cancer tissues." (PMID 35534547, 2022).